IRF3 (interferon regulatory factor 3)
Diseases named in the same sentence as IRF3 in open-access papers (continued):
Sharing a sentence is not in itself a finding about the gene and the disease.
lung adenocarcinoma (continued). "Additionally, down-regulated expression of GATA-1 protein might be responsible for the up-regulation of IRF-3 expression in lung adenocarcinoma cell lines which is in accordance with the observation in our Oncomine analysis and lung adenocarcinoma samples." (PMID 28566697, 2017). "In accordance, IRF3 negatively correlates with the hyperactivation of Wnt signaling in tissues from CRC, lung adenocarcinoma, and hepatocellular carcinoma patients." (PMID 33188184, 2020). "To evaluate the correlation of IRF3 expression and Wnt signaling in human cancers, we examined protein expression levels of IRF3, TCF138, and LEF139 in human CRC (n = 115) and lung adenocarcinoma (n = 67) by tissue microarray-based IHC." (PMID 33188184, 2020). "We conducted cDNA microarray analysis by using the Oncomine database to explore gene expression of IRF-3 and GATA-1 in lung adenocarcinoma." (PMID 28566697, 2017). "In summary, our study implied that TSA enhanced IRF-3 gene expression through increased GATA-1 recruitment to IRF-3 promoter and the acetylation level of GATA-1 in lung adenocarcinoma A549 cells." (PMID 29100282, 2017). "We further investigated their relationship in lung adenocarcinoma cell lines and found that suppression of endogeneous GATA-1 increased the IRF-3 transcriptional activity through the GATA-1 element in the IRF-3 promoter." (PMID 28566697, 2017). "In this study, we found a specific GATA-1 binding site in IRF-3 promoter and observed aberrant gene expression of IRF-3 and GATA-1 in lung adenocarcinoma." (PMID 28566697, 2017). "The Oncomine database was queried for IRF-3 and GATA-1 expression in lung adenocarcinoma and normal tissue." (PMID 28566697, 2017). "In this study, we demonstrated treatment of lung adenocarcinoma A549 cells with trichostatin A (TSA) and valproic acid (VPA), two different classes of histone deacetylase inhibitors, strongly stimulated IRF-3 gene expression." (PMID 29100282, 2017). "We found elevated IRF-3 and decreased GATA-1 gene expression in lung adenocarcinoma in Oncomine database." (PMID 28566697, 2017). "We have previously shown that HEV can elicit inflammatory responses in human lung adenocarcinoma (A549) cells via TLR adaptors, TRIF and MyD88 and activate interferon regulatory factor 3 (IRF3) and NF-κB13." (PMID 27230536, 2016). "Based on our finding that STAT2 preferentially inhibits the induction of IRF3-dependent genes, we propose that the IKKi-induced T404 phosphorylation of STAT2 mediates tumor progression in lung adenocarcinoma by inhibiting the tumor-suppressive function of the cGAS–STING pathway." (PMID 37036972, 2023).
atherosclerosis (10 papers, 2012 to 2025). A disease characterized by the build-up of fatty material and calcium deposition in the arterial wall resulting in partial or complete occlusion of the arterial lumen. "In detail, GSDMD activation leads to mitochondrial rupture and mtDNA leakage, which in turn activates the stimulator of interferon genes (STING)- interferon regulatory factor 3 (IRF3)/NF-κB axis to mediate atherosclerosis progression." (PMID 40356915, 2025). "IRF3 knockout significantly decreased the development of atherosclerosis in hyperlipidaemic ApoE-/- mice, which reduced necrotic core size, macrophage infiltration, lipids, and inflammation." (PMID 38164186, 2024). "cGAS―STING―PERK―IRF3/NF-κB―vascular endothelial dysfunction and atherosclerosis." (PMID 41153813, 2025). "IRF3 promotes the development of atherosclerosis in humans and mice." (PMID 38164186, 2024). "Recent research has shown enhanced expression of GSDMD in atherosclerosis, where it can mediate the cGAS/STING/TBK1/IRF3/NF-κB signaling pathway, contributing to the process of atherosclerosis." (PMID 39301029, 2024). "Upregulation of IRF3 expression has been observed in the endothelial cell layer of atherosclerotic arteries and macrophages in atheromatous plaques from patients with coronary heart disease and hyperlipidaemic ApoE-/- mice (mice with HFD-induced atherosclerosis)." (PMID 38164186, 2024).
colitis (10 papers, 2017 to 2025). Inflammation of the colon. "By suppressing STING oligomerization, it blocks TBK1 recruitment and IRF3/NF-κB nuclear translocation, thereby slowing colitis progression and colitis-associated colon cancer." (PMID 40621423, 2025). "IRF3 deficient mice exhibit severe colitis, showing that dysregulation of IRF/IFN-I signaling is involved in the pathogenesis of IBD." (PMID 35055106, 2022). "IRF3-deficient mice show lethal defects during the inflammatory and recovery phases of colitis." (PMID 38130953, 2023). "Treatment with RU.521 can also reduce cGAMP levels and decrease STING, TBK1, and IRF3 phosphorylation during colitis, confirming the potential pathogenic role of cGAS–STING signaling pathway in colitis." (PMID 37566032, 2023). "IFN regulatory factor 3 (IRF3) ameliorates dextran sulfate (DSS)-induced colitis." (PMID 38130953, 2023). "WB results showed that vitamin D intervention reduced the protein levels of STING, IRF3, and IKBα in DSS-induced colitis." (PMID 40563965, 2025). "The phosphorylation of STING and activation of downstream transcription factors, including interferon regulatory factor 3 (IRF3), nuclear factor kappa-B (NF-κB), and IRF7, were all significantly elevated in colitis." (PMID 39113810, 2024). "Both IRF3 and NF-κB are required for STING-mediated expression of IL-12 family cytokines, promoting Th1 and Th17 differentiation and contributing to excessive inflammation in colitis." (PMID 39113810, 2024). "IRF3 and IRF7 are important for induction of IFN-λ, IFN-α/β, and ISGs; experiments in IRF3/IRF7 double knockout mice with DSS colitis showed greater tissue inflammation relative to controls, suggesting a mucosal protective effect of IFN responses in colonic tissues." (PMID 34712246, 2021). "Anti-inflammatory effects of scoparone in a rat model of colitis have also been reported, while in BV2 microglial cells, scoparone attenuated LPS-induced neuroinflammatory responses by blocking interferon regulatory factor 3 (IRF3) and extracellular signal-regulated kinase (ERK) activation." (PMID 35211087, 2021).
glioma (9 papers, 2013 to 2025). A benign or malignant brain and spinal cord tumor that arises from glial cells (astrocytes, oligodendrocytes, ependymal cells). "For example, isocitrate dehydrogenase 1 (IDH1) mutations in gliomas inhibit interferon regulatory factor 3/7 (IRF3/7) expression, thereby attenuating type I interferon responses." (PMID 41425703, 2025). "Overall, our study reveals a hitherto unrecognized link between IDH1 mutation and IRF3/7 in antiviral immunity and provides a theoretical basis for clinical treatment of IDH1mut gliomas by oncolytic viruses." (PMID 37880243, 2023). "Our study reveals an important additional function for IDH1 mutation in regulating IRF3/7 expression and could help explain the enhanced susceptibility of IDH1mut gliomas to oncolytic viruses." (PMID 37880243, 2023). "On the contrary, overexpression of DNMT1 promoted VSVΔ51 replication and suppressed IRF3/7 expression in glioma cells." (PMID 37880243, 2023). "Meanwhile, we observed that D2HG cannot further promote the replication in IRF3-knockdown or IRF7-knockdown glioma cells." (PMID 37880243, 2023). "In contrast with our present results, a prior study by Dr. Tarassishin and colleagues reported that IRF3 inhibited glioma proliferation, migration, and invasion in vitro." (PMID 33902005, 2021). "As expected, CK2 inhibition results in downregulation of these ‘pro-invasive’ ECM genes whilst genetic silencing of IRF3 increased glioma invasiveness." (PMID 34070023, 2021). "In contrast, IRF3, activation of which exerts strong effects on IL-1/IFNγ-induced inflammatory gene expression and suppresses glioma migration and invasion, is downregulated in glioblastoma cells." (PMID 33902005, 2021). "We discovered that DNMT1 is critical for D2HG-induced IRF3/7 downregulation and may serve as a potential biomarker predicting which IDH1mut gliomas are most likely to respond to oncolytic viruses." (PMID 37880243, 2023). "Finally, we examined the protein expression of IRF3 in tumor tissues from 122 glioma patients, and found that the relative IRF3 expression was significantly lower in IDH1mut gliomas compared with IDH1wt gliomas." (PMID 37880243, 2023). "This intriguing finding implicates the notion that increasing IRF3 expression, associated with a concomitant blockade of CK2 activity, could be exploited as innovative approach to reduce glioma invasiveness." (PMID 34070023, 2021). "The top five TFs with the highest correlations in both datasets consisted of STAT1, MEOX2, CREM, NR2F2, and IRF3, indicating that they were likely to regulate the expression of SERPINF1 in glioma." (PMID 36980858, 2023). "Furthermore, we found that IDH1(R132H) decreased the transcription of IRF3/7 and downregulated the production of IFN-α and IFN-β in glioma cells." (PMID 37880243, 2023). "Among the 260 grade II, 267 grade III, and 173 grade IV glioma patients, significant correlations were observed between IRF1 (p = 8.00E-61), IRF2 (p = 6.80E-18), IRF3 (p = 1.70E-23), IRF5 (p = 2.30E-08), IRF7 (p = 1.90E-29), IRF8 (p = 0.029), IRF9 (p = 4.80E-05) expression and pathological grade." (PMID 33902005, 2021). "Overall survival curves indicated that glioma patients with lower IRF1 (p = 4.42E-33), IRF2 (p = 2.22E-16), IRF3 (p = 1.43E-15), IRF4 (p = 0.004), IRF5 p = 5.84E-12), IRF7 (p = 6.85E-28), IRF8 (p = 0.001), and IRF9 (p = 0.000) transcript levels had significantly longer overall survival times." (PMID 33902005, 2021).
Hepatic steatosis (9 papers, 2016 to 2025). Steatosis is a term used to denote lipid accumulation within hepatocytes. "Elevated IFN-I signaling in the liver, including the expression of IRF3, has been shown to correlate with fatty liver diseases in humans and glucose intolerance and dysregulated hepatic metabolism in mice." (PMID 35015731, 2022). "IRF3 knockout protects experimental rabbits from the development of alcohol-induced hepatic steatosis, alcoholic hepatitis, and liver injury." (PMID 27448985, 2016). "Additionally, they observed that IRF3 whole-body knockout ameliorated liver injury in ALD mice by alleviating liver steatosis and inflammation." (PMID 38694821, 2024). "Some research suggests that cytoplasmic IRF3 interacts with IKKβ, inhibiting NF-κB activation, and that reduced IRF3 levels may protect hepatocytes from HFD-induced hepatic steatosis, inflammation, and macrophage infiltration." (PMID 39669992, 2024). "Therefore, in the context of alcohol-mediated hepatic steatosis, the autophagic degradation of IRF3 can be beneficial." (PMID 36507301, 2022). "Of note, apart from binding to ISRE promoter elements, IRF3 has been reported to bind ISRE-like elements and activate the RANTES promoter, or bind to IRF3-binding sites within the SCD1 promoter to repress Scd1 transcription and prevent hepatic steatosis." (PMID 40431610, 2025). "They found that chronic alcohol-fed TLR4 knockout mice showed reduced liver damage, including less hepatic steatosis, lower levels of liver enzymes, and decreased expression of liver TNF-α, IL-6, IRF3, and IRF7 compared to WT, TLR2 knockout, and MyD88 knockout mice." (PMID 38694821, 2024). "IRF3’s role in alcohol-induced fatty liver diseases has been studied extensively; the non-transcriptional pro-apoptotic activity of IRF3 plays a detrimental role by killing hepatic cells." (PMID 36507301, 2022).
hepatocellular carcinoma (9 papers, 2010 to 2025). A malignant tumor that arises from hepatocytes. "WCL harboring promoted vaccinia virus replication and production of type I IFNs via upregulation of IRF-3 activity in hepatocellular carcinoma cells." (PMID 34064193, 2021). "Similar observations were retrieved from human hepatocellular carcinoma patients (n = 92), with inverse relation between IRF3 and TCF1/LEF1, and shorter survival time of patients with low IRF3 and high TCF1 and LEF1 expression." (PMID 33188184, 2020). "IRF-3 is related to TRAIL expression in viral infected hepatoma cell line." (PMID 22087337, 2011). "Similar to IPS-1-HeLa cells, we observed that hepatocellular carcinoma SKHep1 cells NDV, SeV, Influenza virus, or Sindbis virus infection also induced a speckled staining pattern in endogenous IPS-1, and displayed enhanced IRF-3 dimerization when compared with HeLa cells (our unpublished data)." (PMID 20661427, 2010).
liver fibrosis (9 papers, 2016 to 2025). "Interfering IRF3 activity by targeting GPCR will represent a novel pharmacological approach for liver fibrosis and other diseases associated with IRF3 dysregulation." (PMID 38233853, 2024). "IRF3 and target genes were strongly associated with fibrosis markers in liver fibrosis patients and models." (PMID 38233853, 2024). "Abnormal increase in IRF3 activity in hepatocytes has been linked with diseases, particularly in liver fibrosis." (PMID 38233853, 2024). "The association of other transcripts such as CD70, IFNE and IRF3 with liver fibrosis has been scarcely reported." (PMID 27135246, 2016). "Since GPCRs have been the primary targets for recent development of therapeutic drugs, our results provide valuable pharmacological insights into the regulation of IRF3 and diseases involving activated IRF3 such as liver fibrosis." (PMID 38233853, 2024). "To determine the role of hepatic IRF3 in liver fibrosis, we first analyzed the transcriptomic profiles of fibrosis patients (GSE25097)." (PMID 38233853, 2024). "An experimental model of liver fibrosis using chronic administration of carbon tetrachloride also results in IRF3 activation." (PMID 38233853, 2024). "Our results show that IRF3 is involved in liver fibrosis and activates hepatic stellate cells through intercellular signaling." (PMID 38233853, 2024). "IRF3 is associated with STING in the presence of ER stress and combines hepatocyte apoptosis with liver fibrosis, indicating that innate immune signals regulate the outcomes of liver fibrosis by regulating hepatocyte death in the liver." (PMID 34386500, 2021). "However, how hepatocyte IRF3 regulates liver fibrosis or trandifferentiation of HSCs, the cells primarily responsible for fibrogenesis in the liver, is poorly understood." (PMID 38233853, 2024). "Our findings that hepatocyte GPCR signaling regulates IRF3 to control hepatic stellate cell transdifferentiation provides an insight for understanding the complex intercellular communication during liver fibrosis progression and suggests therapeutic opportunities for the disease." (PMID 38233853, 2024). "Interestingly, total knockdown or conditional deletion of IRF3 in HSC exacerbated liver fibrosis, indicating a dual role for IRF3 in this process that required further investigation." (PMID 38999981, 2024). "On the other hand, IRF3 knockout mice are resistant to develop liver fibrosis in the same model." (PMID 38233853, 2024). "Our decision to test the effects of IRF3 knockdown on macrophage polarization was based on preceding publications demonstrating the protective effect of the global knockout of IRF3 on ethanol-induced liver fibrosis and in acute or chronic CCl4-induced liver injury." (PMID 36010574, 2022). "Therefore, IRF3 may be an attractive therapeutic target for liver fibrosis which interferes with pathological intercellular communication in the liver." (PMID 38233853, 2024). "In this study, IFNα, IFNβ, ISG15, USP18, IFN-induced protein 44 (Ifi44), interferon-induced protein with tetratricopeptide repeat (Ifit) 1, Ifit2, IRF3, and IRF7 were significantly elevated in the CCl4-induced liver fibrosis model." (PMID 40260261, 2025). "Acute administration of CCl4 in WT mice results in early ER stress, IRF3 activation, and type I IFN induction, followed by hepatocyte apoptosis and liver damage, with liver fibrosis occurring after repeated administration of CCl4." (PMID 34386500, 2021). "Moreover, ER stress could induce hepatocyte apoptosis to promote liver fibrosis via stimulator of interferon genes (STING) and interferon regulatory factor 3 (IRF3), which could explain why the pro-apoptosis gene CHOP was highly expressed in HCV patients with liver fibrosis." (PMID 33015132, 2020).
Stroke (9 papers, 2011 to 2025). Sudden impairment of blood flow to a part of the brain due to occlusion or rupture of an artery to the brain. "In particular, the evidence presented here further highlights a key role for IRF3 activity in the protective response to stroke." (PMID 21999375, 2011). "Evidence presented here and previously suggests that signaling following stroke is redirected towards IRF3." (PMID 21999375, 2011). "As TRIF signaling culminates in IRF3 activation, this finding provides further evidence for the importance of IRF3 in the neuroprotective response to stroke." (PMID 21999375, 2011). "LPS preconditioning redirects TLR4 signaling in response to stroke through suppression of NFκB activity, enhanced IRF3 activity, and increased anti-inflammatory/type I IFN gene expression." (PMID 21999375, 2011). "These divergent findings highlight the cGAS/STING/IRF3 pathway’s pivotal role in post-stroke immune regulation, orchestrating immune cell activation, cytokine dynamics, neuroinflammation, apoptosis, and tissue repair during stroke recovery." (PMID 41471264, 2025). "In contrast, IRF3 activity was enhanced in LPS-preconditioned mice following stroke." (PMID 21999375, 2011). "Thus, targeted modulation of STING/IRF3 pathway may promote neural repair in stroke recovery." (PMID 41471264, 2025). "Stroke leads to upregulation of STING expression, activation of TBK1 and IRF3, and induction of IRF3-dependent IFN-β synthesis." (PMID 34335600, 2021). "Our data revealed that stroke led to upregulation of the DNA sensor STING, activation of TBK1 and IRF3, and induction of the IRF3-dependent IFN-β synthesis." (PMID 32427863, 2020). "Using an IRF3 activity ELISA, we determined that IRF3 activity is comparable immediately prior to stroke (data not shown) and subsequently enhanced in the brains of LPS-preconditioned mice following MCAO." (PMID 21999375, 2011). "Therefore, stroke-induced TLR4 signaling may be blocked completely, leading to reduced injury, and stroke-induced TLR4 signaling would shift from NF-κB induction to IRF3 induction." (PMID 21982558, 2011).